CD24 (CD24 molecule)
Diseases named in the same sentence as CD24 in open-access papers (continued):
Sharing a sentence is not in itself a finding about the gene and the disease.
breast cancer (continued). "Moreover, CD24 expression is suggested to be a marker of poor prognosis in various cancers, including breast carcinoma." (PMID 18433506, 2008). "Similarly, CD24 has been shown to promote or inhibit invasion and metastasis of breast cancer cells." (PMID 17062128, 2006). "Possibly, CD24-expressing tumour cells can spread more easily because of their capacity to either form thrombi with activated platelets or to adhere to endothelia in the bloodstream as demonstrated for CD24-expressing breast cancer cells." (PMID 12610508, 2003). "Pathologically, CD24 has been described in B-cell neoplasia, renal cell carcinoma, small cell lung cancer, nasopharyngeal carcinoma, hepatocellular carcinoma, bladder carcinoma, glioma, breast cancer and ovarian cancer." (PMID 12610508, 2003). "Moreover, HER2 and CD24 are both expressed in normal tissues and other cancers, including ovarian and gastric cancers, which could limit the clinical specificity of HER2+ and CD24+ EVs as biomarkers of breast cancer." (PMID 40405296, 2025). "In human cancer cells, CD24 can interact with P-selectin after proper modification of carbohydrates (such as sialic acid-Lex), encouraging the attachment of ovarian cancer cells to the mesothelium and allowing breast cancer cells to roll and adhere to platelets on endothelial cells." (PMID 40486886, 2025). "Evidence from in vitro studies demonstrated that the overexpression of CD24 was associated with the inhibition of stem-like properties in breast cancer cells, and another study suggested that the lack of CD24 in breast cancer cells was associated with resistance against chemotherapeutics." (PMID 40869256, 2025). "Moreover, there is data on the prognostic value of CD24 expression on CTCs in breast cancer." (PMID 38806508, 2024). "In breast cancer, the absence of CD24 is associated with a CSC phenotype." (PMID 38360723, 2024). "Interestingly, studies have demonstrated that adding B27 to the culture media in non-adherent conditions improves tumoursphere formation efficiency and enhances the enrichment of the CD44 + /CD24–/low lineage, which can reach up to approximately 95% in breast cancer cell lines." (PMID 39003349, 2024). "However, only CD24 was detected in the EVs isolated from the serum of breast cancer patients." (PMID 37629204, 2023). "However, several studies conversely suggested that the absence or low expression of CD24 might be also related to tumor growth, invasiveness or metastasis in breast cancer." (PMID 37919766, 2023). "Moreover, CD24 expression in breast cancer has shown a positive correlation with tumor grading." (PMID 36979874, 2023). "Therefore, researchers should further characterize CD24 function in the tumor biology of different phenotypes for better understanding of the mechanisms and developing novel, effective targeted therapies to improve outcome of breast cancer patients." (PMID 37919766, 2023). "Additionally, breast cancer cells overexpress CD24, while TAMs express high levels of Siglec‐10." (PMID 34914196, 2022). "Interestingly, mammospheres formed from patient-derived primary breast tumors were enriched in breast cancer stem-like cells with the phenotype CD44+/CD24-/low and exhibited a relatively more number of large spheres when compared to the normal breast stem cells." (PMID 36504339, 2022). "Besides, in RNF31 knocking down background, RNF31 overexpression could decrease the proportion of CD44+/CD24- breast cancer cells." (PMID 36581998, 2022). "Interestingly, another study argued that a high CD44/CD24 ratio was mainly in charge of cell proliferation and tumorigenesis in breast cancer, while the aldehyde dehydrogenase 1 (ALDH1)-positive phenotype was significantly associated with cell migration and metastasis." (PMID 33801148, 2021).
breast cancer (continued). "Indeed, a xenograft study using nude mice and other in vivo experiments have reported that disseminated tumor cells in the bone marrow of breast cancer patients showed a high CD44+/CD24- ratio and the elevated expression of CD44+/CD24- was closely associated with lung metastasis." (PMID 33861751, 2021). "A recent study reported a significant increase in the percentage of CD44+/CD24–/low breast CSCs in biopsies specimens following chemotherapy, suggesting that modulating Notch in breast cancers may be a promising strategy to reduce drug resistance by eliminating the CSC subpopulation." (PMID 33681228, 2021). "CD24 overexpression is associated with histone acetylation and is an independent poor prognostic factor in TNBC; importantly, CD24 may be a potential therapeutic target for this type of breast cancer." (PMID 34198989, 2021). "Co-culture of either wild type or ΔCD24 breast cancer cells with M2 revealed that CD24 deletion alone is sufficient to potentiate phagocytosis, while interfering CD24 or Siglec-10 could significantly enhance the phagocytic function of macrophages on CD24+ tumors and restrain the growth of tumor." (PMID 34625124, 2021). "Furthermore, CD24 increases tumor cell proliferation, and it shows increased cell adhesion to fibronectin, collagens I and IV, and laminin through the activation of α3β1 and α4β1 integrin activity in breast cancer." (PMID 34360932, 2021). "Moreover, these AML cells could be enriched by using a combination of the cell surface markers CD34+CD38-2, while breast cancer-propagating cells were marked with CD44+CD24-/low3." (PMID 32754274, 2020). "IL-6 secretion is crucial for CSC maintenance and sufficient to induce the CD44 + /CD24 low phenotype in breast cancer cell lines and tumors, this supporting the idea that the IL-6-JAK2-STAT3 signal transduction pathway could play an important role in the conversion of non-CSCs into CSCs." (PMID 30728463, 2019). "Immunofluorescence analysis showed loss of CD24 expression in MPS derived from vMCF-7Raf-1 1GX-M cells compared with parental cells, demonstrating that loss of CD24 expression is linked to higher tumor self-renewal capacity and plasticity of metastatic breast cancer cells." (PMID 30180881, 2018). "Indeed, CD24 is expressed in a variety of malignancies including B-cell lymphoma, renal-cell carcinoma, nasopharyngeal carcinoma, hepatocellular carcinoma, bladder carcinoma, glioma, ovarian, and breast cancer." (PMID 28360912, 2017). "The outcome indicated that exosomal CD24 could serve as a circulating breast cancer biomarker." (PMID 28085080, 2017). "While exact methods of identifying of these mammary stem cells is still debated, many agree that high CD44 expression, low CD24 expression, low CD49f expression, and the ability to form mammospheres are excellent indicators of individual mammary stem cells and potentially breast cancer stem cells." (PMID 27542214, 2016). "Furthermore, CD24 deficiency in Apc1572T/+ mice slightly but statistically significantly reduced tumor burden, whereas no such effect was observed in MMTV-PyMT mice, suggesting that CD24 may play different roles in different types of breast cancer." (PMID 26978528, 2016). "However, most studies have not assessed the association of CD24 expression with patient outcome according to molecular subtypes of breast cancer and the prognostic significance of CD24 expression in each subtype of breast cancer remains unclear." (PMID 26444008, 2015). "This study also revealed that CD24 downregulation by siRNA sensitises HER2-positive breast cancer cells to lapatinib, a HER2-targeted therapy, supporting the idea that targeting CD24 in combination with HER2-targeted therapy might enhance the efficacy of HER2-targeted agents." (PMID 26444008, 2015).
breast cancer (continued). "Taken together, these results illustrated that the effect of CD24 expression on clinical outcome differs according to molecular subtypes, and CD24 may have a time-dependent effect on patient survival in different subtypes of breast cancer." (PMID 26444008, 2015). "Because CIN in breast cancer is mechanistically linked to development of centrosome abnormalities, we analyzed the grade of centrosome amplification in bulk SUM149PT cancer cells versus the stem-like CD44+/CD24−/Low subpopulation isolated by FACS sorting assay." (PMID 24970653, 2014). "Also, HER2 can be clinically correlated with stem/progenitor cell populations in that patients with HER2+ breast cancers treated with the HER2 inhibitor lapatinib show a significant reduction in the number of CD44+/CD24–/low cells and a decreased tumorsphere-forming efficiency." (PMID 25209720, 2014). "Thus, there are possibilities that Alu and LINE-1 hypomethylation may be different according to breast cancer subtype or CD44+/CD24− and ALDH1+ breast cancer stem cell (BCSC) phenotypes." (PMID 24971511, 2014). "Cell populations enriched with breast cancer stem cells can be identified by expression of specific sets of marker proteins such as nucleostemin and aldehyde dehydrogenase-1 (ALDH-1), which are associated with maintenance and self-renewal properties, and by their CD44+/CD24-/low phenotype." (PMID 25209720, 2014). "However, the role of STAT3 signaling in ALDH+ and ALDH+/CD44+/CD24− subpopulations of breast cancer cells is unknown." (PMID 24376586, 2013). "In addition, a previous study reported that NDRG2 could inhibit the metastatic potential of breast cancer cells, specifically via the suppression of CD24 or MMP-9 expression." (PMID 23800335, 2013). "Therefore, the development of therapies eliminating CD44(+)/CD24(-/low) CSCs or impeding activation of the signaling pathways these cells rely on may represent a promising approach for basal-like breast cancer." (PMID 24392029, 2013). "Interestingly, it was recently published that autophagy promotes the undifferentiated stem-like CD44+/CD24-/low phenotype in breast cancer cells and further evidence for the involvement of autophagy in cancer stem-like cell maintenance as well as their differentiation is accumulating rapidly." (PMID 24229464, 2013). "It is therefore necessary to understand the reasons for CD44+/CD24- breast cancer cells in bone: whether CTCs are CD44+/CD24- CSCs that preferentially migrate and establish metastases, or if non-CD44+/CD24- CTCs are induced to the CD44+/CD24- phenotype in the bone marrow." (PMID 22934288, 2012). "Notably, the bone marrow microenvironment is enriched in TGF-β, a cytokine that is well-known to induce EMT, and production of TGF-β by microenvironment stromal cells may be responsible for CD44+/CD24- breast cancer cells in bone." (PMID 22934288, 2012). "In a review of existing literature on the role of CD44/CD24 in recurrent human cancer, investigators showed positive associations between CD44+/CD24- and prognosis, especially in breast cancer; and the CD44+/CD24- phenotype of breast cancer cells was also associated with invasive properties." (PMID 22839505, 2012). "CD44+CD24-/low expression showed association with death due to breast cancer (p = 0.035) but not with age (p = 0.789), menopausal status (p = 0.131), clinical stage (p = 0.219), histological grade (p = 0.319), lymph node status (p = 0.895), recurrence (p = 1.000), or distant metastasis (p = 0.479)." (PMID 21824412, 2011). "However, there are no overlapping genes between our results and the gene signature identified by gene expression profiling of CD44+CD24- breast cancer stem-like cells; therefore, our findings should be validated in further studies, for example, analysis of stem cell marker expression." (PMID 20696077, 2010).
breast cancer (continued). "Al-Hajj's research in 2003 has shown that breast cancer stem cells (ESA+CD44+CD24-/low, BCSCs) possessing the stem cell properties of self-renewal and multi-directional differentiation are the most fundamental contributors to drug resistance, recurrence and metastasis of breast cancer." (PMID 21192833, 2010). "Moreover, immune-mediated induction of EMT in epithelial breast cancer cells resulted in a mesenchymal population with the breast cancer CSC immunophenotype CD24−/loCD44+ as well as the capacity to repopulate the malignancy after transplantation of low cell numbers." (PMID 20664590, 2010). "Work on breast cancer cell lines suggests that the radio resistance of the CD44+/CD24- subset of cells with stem-like characteristics might be related to increased activation of Notch, a molecule reported to protect normal and breast cancer cells against diverse apoptotic stimuli." (PMID 20426848, 2010). "However, the specific functions of CD24 in breast cancer are unclear." (PMID 18433506, 2008). "We conclude that CD24 may be considered as a novel therapeutic target for breast cancer." (PMID 18433506, 2008). "Accumulating evidence supports a role for CD24 in a variety of malignancies, including B-cell lymphoma, renal cell carcinoma, small-cell and non small-cell lung carcinoma, nasopharyngeal carcinoma, hepatocellular carcinoma, bladder carcinoma, epithelial ovarian cancer and breast cancer." (PMID 18433506, 2008). "It is possible that CD24 in vivo may be a novel target for breast cancer treatment." (PMID 18433506, 2008). "We investigated whether breast cancer cells with the CD44+/CD24- phenotype possess three essential characteristics of cells with metastatic phenotype: expression of invasion/metastasis-associated genes; invasion; and homing and proliferation at sites of metastasis." (PMID 17062128, 2006). "We found 24 individual miRNAs that had significant predictive value to classify women with breast cancer, including miR-340-5p from HER2+ EVs with an AUC of 0.87 and miR-223-3p from CD24+ EVs with an AUC of 0.75." (PMID 40405296, 2025). "To examine the stem features of the different breast cancer cell lines, we assessed the expression of CD44, CD24 and ALDH1 in both MCF-7 and MDA-MB-231 cell lines using FACS." (PMID 39955575, 2025). "In breast cancer tissues, high expression of CD44+/CD24- can increase the invasiveness of breast cancer cells and promote tumor recurrence and distant metastasis." (PMID 41019994, 2025). "The upregulated differentially expressed breast cancer stem cell markers included CD56/NCAM1, POU5F1, PROCR/CD201, ITGA6, and the downregulated were ESR1, PGR, HER2/ERBB2, ABCG2, CD44, CD24, EPCAM, and CDH1." (PMID 40690373, 2025). "Gene expression correlation analysis revealed that USP30 negatively correlates with the expression of stem cell markers such as MMP2, MMP9, MYC, OCT4(POU5F1), NANOG, ALDH1A3, CD133 (PROM1), EPCAM, CD24, and ITGA6 in breast cancer cohorts." (PMID 41306556, 2025). "In this study, six CSC markers (CD44hi/CD24lo, CD24, Ep-CAM, ALDH1, CD10, and BMI1) were assessed in a surgical cohort of 73 breast cancer patients." (PMID 40943144, 2025). "This investigation delineates a distinct C4 cellular subpopulation within ER+ breast cancer, identified via single-cell transcriptomic profiling and defined by the co-expression of MUCL1 and CD24." (PMID 41142825, 2025). "The most consistently used biomarkers for identifying breast cancer stem cells (BCSC) are CD44, CD24, and ALDH1." (PMID 40707430, 2025). "In the checkpoint module, CD24 and VTCN1 were recognized as more active signaling pathways related to immune escape in breast cancer with high RiskScore." (PMID 40337509, 2025). "To investigate the effect of propofol and FOXO3 on breast cancer cell stemness, we analyzed the percentage of ESA+/CD44+/CD24-/low cells by flow cytometry." (PMID 39991565, 2025).
breast cancer (continued). "By capturing darkfield images and performing analysis using in-house machine learning pipeline, a successful diagnosis and differentiation of HER2-positive breast cancer at Stages II, III, and IV was established based on CD24 and EpCAM expression levels." (PMID 41404198, 2025). "In the TCGA breast cancer dataset, SDC1 expression was notably correlated with the stem cell biomarkers CD133, CD44, CD24, POU5F1, SMAD2, and NANOG at the transcriptional level." (PMID 41364407, 2025). "CD24, a critical breast stem marker, which is lowly expressed in aggressive HER2-positive breast cancer, was also downregulated." (PMID 40946111, 2025). "Breast cancer stem cells (BCSCs) exhibit distinct marker profiles defined by CD44, CD24, and ALDH expression." (PMID 41373619, 2025). "FGF13-AS1 expression is reduced in breast cancer tumors compared with adjacent healthy tissue and is correlated with unfavorable prognosis and a higher proportion of BCSC (CD44+/CD24−)." (PMID 41181715, 2025). "LASSO classification selected a panel of four complementary EV miRNA for classifying breast cancer: miR-340-5p (HER2+ EVs), miR-598-3p (CD24+), miR-15b-5p (HER2+), and miR-126-3p (CD24+)." (PMID 40405296, 2025). "Our study suggests that the downregulation of the CD24 and upregulation of miR590-3p might indicate poor therapy response, and their further decrease and increase after therapy might be early and poor prognostic factors for therapy resistance in breast carcinoma." (PMID 40587726, 2025). "The pre- and posttreatment expression levels of CD44, CD24, miR590-3p, miR599, and miR399-3p by pathologic response in HER2+ subtype of breast carcinoma." (PMID 40587726, 2025). "In breast cancer, this pathway is pivotal for the development of human CD44+CD24- stem cell-like cancer cells, and the inhibition of JAK2 prevents xenograft growth." (PMID 39079960, 2024). "In this study, we showed that in two breast cancer cell lines – MDA-MB-231 and MCF-7 – subpopulations with the CD44+/CD24- surface marker phenotype have increased miR-10b expression relative to their parental cell line or other subpopulations." (PMID 39189967, 2024). "Consistently, TNBC is histologically poorly differentiated and displays enhanced stemness compared to other breast cancer subtypes, as evidenced by a higher proportion of CD44+CD24− and ALDH+ breast cancer stem cells (BCSCs)." (PMID 39563370, 2024). "In breast cancer, populations with CD44+CD24-/low surface markers and high ALDH1 activity are enriched for cells with stem cell properties." (PMID 38886396, 2024). "On the other hand, CD24 expression is downregulated by Twist, -catenin/TCF, miR-34a and miR-146a, and histone deacetylase (HDAC) in breast cancer, colorectal, oral squamous cell carcinoma, and HDAC-positive colorectal cancer, respectively." (PMID 38279998, 2024). "The cell surface markers CD44+/CD24- are widely used to identify and isolate CSCs from breast cancer, whereas CD44+/CD24-enriched CSCs have been found in mesenchymal TNBC." (PMID 39201646, 2024). "Breast cancer stem cells (BCSCs) can easily switch between the ME phenotype EpCAM+CD49f+ ALDH1+, and EM phenotypeEpCAM− CD49f+ are positive for CD44/CD24." (PMID 39238997, 2024). "Some biomarkers, which have been mentioned here, and researched for their clinical utility in locating and characterizing breast cancer include EGFR, HER2, ER, CD24, CD44, and CD47." (PMID 40051976, 2024). "For example, expression of CD44, CD24, and ALDH1A3 can quantify epithelial and mesenchymal stem cell states in breast cancer and normal breast tissue." (PMID 38915368, 2024). "SMS2 decreased the CD24 transcription level but increased the transcription levels of stemness-related genes including CD44, ALDH, OCT 4 and SOX2 in breast cancer cells." (PMID 38285090, 2024).